BRAF (B-Raf proto-oncogene, serine/threonine kinase)
Diseases named in the same sentence as BRAF in open-access papers (continued):
Sharing a sentence is not in itself a finding about the gene and the disease.
melanoma (continued). "The most common genetic alteration in melanoma is the BRAF V600 mutation, which is estimated to account for approximately 50% of all melanomas in Caucasian patients." (PMID 38358050, 2024). "These treatments are effective because they block the hyperactivated MAPK pathway in BRAF-mutated melanomas." (PMID 39859956, 2024). "In melanoma, thyroid cancer, and histiocytic neoplasms, BRAF hotspot mutations are found at a rate of about 50%, while in lung and colorectal cancers they range from 3% to 10% of reported cases." (PMID 38539548, 2024). "BRAF-V600E mutations were observed in almost all melanoma cell lines except for the SK-Mel-2 cell line." (PMID 38519031, 2024). "In this study, A375 and FO-1, BRAF-mutated melanoma cell lines, were treated for 4–5 months with RAF inhibitor dabrafenib or AZ628, leading to drug resistance over time." (PMID 39596009, 2024). "For example, activating mutations in B-RAF (BRAF) have been identified in approximately 50% of melanoma." (PMID 39372954, 2024). "Earlier works by others have demonstrated that advanced melanoma patients with BRAF mutations not only have an increased risk of developing BrM, but also have a shorter disease-free interval from primary diagnosis to diagnosis of BrM." (PMID 38730723, 2024). "Although BRAF is one of the most common mutations, our findings show that relying just on BRAF to characterize advanced melanomas is quite limiting." (PMID 38667446, 2024). "According to the Clark model, which describes the histopathological changes occurring during normal melanocytes’ linear progression to melanoma via a benign naevus, BRAF mutations have a crucial role in melanoma development and progression." (PMID 38396984, 2024). "Dabrafenib is an inhibitor of some mutated forms of BRAF kinases, including BRAF V600E, often found in melanoma." (PMID 39682138, 2024). "This latter type of treatment is associated with a more rapid response but can only be used in melanomas that harbour an activating BRAF V600E mutation, and, unfortunately, resistance to treatment installs rapidly, after a median duration of 11 months." (PMID 39001214, 2024). "Combining a MEKi with a BRAFi has shown enhanced efficacy in inhibiting tumor growth, delaying acquired resistance development, and eliminating paradoxical activation of the MAPK pathway in preclinical models of BRAF-mutated melanoma." (PMID 39582535, 2024). "Alternatively, BRAF expression was shown to be associated with lymph node metastasis in patients with melanoma and papillary thyroid carcinoma." (PMID 38919805, 2024). "The second study searched for the cause of resistance of A375 melanoma cells to the BRAF inhibitor vemurafenib." (PMID 38255778, 2024). "Numerous studies have demonstrated that dabrafenib and trametinib combined therapy are the best options for melanoma patients with BRAF mutations, and superior outcomes were verified in multiple clinical trials." (PMID 39025927, 2024). "Human melanoma A2058 and A375 cells harbor the tumor-driving BRAF(V600E) mutation, which is present in approximately 50% of human melanomas and represents a major target in melanoma therapy." (PMID 38474307, 2024). "In contrast, the cutaneous variant known for BRAF mutations is rarely observed in urinary tract melanomas." (PMID 38933829, 2024). "The aim of this study was to determine the usefulness of selected lncRNAs as diagnostic and prognostic biomarkers in melanoma patients with a BRAF V600 gene mutation and undergoing targeted therapy with BRAF inhibitors in combination with MEK inhibitors." (PMID 38601651, 2024). "BRAF V600E mutations in Black patients were less frequent in colorectal cancers, melanoma, and thyroid cancers, but were more frequent in gliomas." (PMID 38297963, 2024). "In 2011, a subcutaneous relapse of the right breast, considered a metastasis in transit, was excised and identified as a BRAF-V600E mutated melanoma." (PMID 39502313, 2024).
melanoma (continued). "Up to 60% of melanomas demonstrate mutations in the BRAF gene, with BRAF V600E being the most common." (PMID 39717410, 2024). "In the case of melanoma, detection of ctDNA by determining the presence of mutations in the BRAF oncogene, which is the majority oncogene in this disease, is suggested." (PMID 39387479, 2024). "Phenformin combined with BRAF and MEK inhibitors is currently undergoing a clinical trial for the treatment of BRAF-mutated melanoma (NCT03026517)." (PMID 38719825, 2024). "In primary melanoma, the most common mutations exist in proto-oncogene B-Raf or v-Raf murine sarcoma viral oncogene homolog B (BRAF), in the rat sarcoma gene (RAS)." (PMID 39195270, 2024). "Oncogenic BRAF mutations are present in around 66% of melanomas and to a lesser extent in some other cancers." (PMID 38345654, 2024). "Melanoma, one of the most aggressive forms of skin cancer, is associated with BRAF gene mutations in roughly 50% of cases, leading to the persistent activation of the BRAF gene." (PMID 39682248, 2024). "It is indicated for the treatment of patients affected by advanced melanoma with BRAF V600 mutations, found in 50% of melanoma cases and associated with increased cell proliferation and increased oncogenic cell activity." (PMID 39464179, 2024). "The MAPK pathway plays a pivotal role in melanoma biology, primarily through the mutational activation of key oncogenes such as BRAF and NRAS." (PMID 39199684, 2024). "Next, we found that DHCR24 induced vemurafenib resistance in BRAF-mutated cells by promoting melanoma spheroid propagation." (PMID 38775844, 2024). "Currently, dabrafenib is indicated as a single agent for unresectable or metastatic melanoma with the BRAF V600E mutation and, in combination with trametinib, for advanced melanoma with BRAF mutations." (PMID 38594618, 2024). "The Food and Drug Administration (FDA) approved it for the treatment of unresectable or metastatic BRAF V600E-mutated melanomas." (PMID 38183141, 2024). "The OFA has been specifically designed to provide comprehensive genomic profiling of solid tumors and includes the mutational study of melanoma-related genes such as BRAF, NRAS, KIT, MAP2K1, or HRAS." (PMID 39000050, 2024). "In multiple settings for BRAF-mutant melanoma, targeted therapy has been associated with a good initial response rate, but a higher risk of treatment failure when compared with patients who respond to immunotherapy." (PMID 38907159, 2024). "In our study, the combination of S63845 with ABT-263, ABT-737, and ABT-199 showed high efficiency both in BRAF-mutated and BRAF-WT melanoma cell lines, as evidenced by induced apoptosis in up to 94% of the cells and almost complete loss of cell viability." (PMID 38542429, 2024). "Melanoma is another solid organ malignancy with relatively high rates of BRAF mutation, estimated to occur in about 50% of cases." (PMID 38814411, 2024). "We applied a macrophage ACT approach similar to SM1 murine melanoma with human humanized NSG-SGM3 mice harboring BRAF V600E mutated human melanoma tumor xenografts." (PMID 39272209, 2024). "The most commonly observed mutation occurs in the BRAF oncogene; since its discovery in 2002, multiple targeted therapies for the treatment of melanoma have been approved." (PMID 39542696, 2024). "Though NF1 mutations are typically seen in melanomas that lack mutations in BRAF or NRAS, nearly 4% of melanomas with mutations in BRAF or NRAS also harbor NF1 mutations." (PMID 38247727, 2024). "Transitioning from binary to scored mutations not only resolved BRAF V600X from other BRAF mutations, but found additional mutations highly predictive of dabrafenib responses in both cell lines and melanoma patients." (PMID 38940147, 2024). "The review discusses the FDA-approved combinations of inhibitors, their impact on treating BRAF-mutated melanoma, and the challenges posed by therapeutic resistance." (PMID 39582535, 2024).
melanoma (continued). "In BRAF-mutated melanoma, a complete shutdown of the MAPK pathway is necessary for significant tumor response." (PMID 36778401, 2024). "These inhibitors have shown effectiveness in patients with melanoma, particularly those with the BRAF V600E mutation." (PMID 38534742, 2024). "The ERBB2 receptor is linked to breast adenocarcinoma, the BCR/ABL fusion gene to chronic myelogenous leukemia, and BRAF (V600E) mutations to melanoma, colorectal cancer, and thyroid cancer." (PMID 39767657, 2024). "Its expression levels were influenced by BRAF mutations and were markedly higher in metastatic compared to primary melanomas." (PMID 39764216, 2024). "In patients diagnosed with stage III or IV melanoma, non-V600 BRAF mutations such as V600R, V600_K601delinsE, K601E, p.T599_V600insT, L597V, G466R, S467L, and A598T were observed." (PMID 39582535, 2024). "BRAF V600 mutations can be observed in approximately 50% of melanoma patients, 40% of papillary thyroid carcinoma patients, and 10% of colorectal cancer patients." (PMID 39529955, 2024). "In melanoma, we found that BRAF Class 1 mutations occur in younger patients compared to Class 2/3 non-V600 BRAF mutations." (PMID 38275886, 2024). "Two PD1 blockades, nivolumab, and pembrolizumab, have been approved by the FDA for use in patients with metastatic melanoma and BRAF-mutated melanoma." (PMID 38956559, 2024). "Regarding target therapy, the treatment of melanoma was revolutionized with the discovery of the BRAF mutation in 2002." (PMID 38201012, 2024). "We studied three human melanoma tumor models that express the BRAF-V600E mutation: WM983BR, WM983B, and DB-1." (PMID 38254853, 2024). "Despite the great diversity of melanoma cell lines, models containing BRAF or NRAS mutations are of great importance." (PMID 38835508, 2024). "Given the prevalence of BRAF gene mutations in many melanoma patients, BRAFV600E inhibitors effectively curb the growth of tumor cells by specifically targeting the activity of this mutated gene." (PMID 39430757, 2024). "Five out of the seven melanoma brain metastases harbored the BRAF V600E mutation, and two out of the seven cases had other less frequent mutations (one NRAS mutation, one KIT mutation)." (PMID 39204387, 2024). "Selective BRAF inhibitor monotherapy and BRAF/MEK inhibitor combinations are more effective than traditional chemotherapy in treating BRAF‐mutated melanoma." (PMID 39564955, 2024). "In conclusion, in agreement with other reports, the present analysis indicated the efficacy of first‐line immunotherapy in patients with BRAF‐mutated malignant melanoma." (PMID 38491825, 2024). "Melanomas that arise against a background of low-CSD typically harbor BRAF V600E mutations (and rarely NRAS Q61 mutations) and originate from benign nevi." (PMID 38396984, 2024). "Approximately 40-60% of melanoma cases harbor V600E mutation in BRAF, resulting in constitutive activation of mitogen-activated protein kinase (MAPK) signaling pathway." (PMID 38778340, 2024). "Our study also highlights the extent of spare signaling capacity in the ERK pathway in melanoma cells with BRAF or NRAS mutations." (PMID 39436655, 2024). "Dabrafenib, which was FDA-approved as a treatment for unresectable or metastatic melanomas with V600E mutations in 2013, has a similar mechanism of action as vemurafenib and also inhibits the BRAF monomer." (PMID 38539548, 2024). "In the past 15 years, enormous progress has been made in the prevention and treatment of metastatic melanoma due to the development of BRAF and MEK inhibitors for BRAF V600-mutated melanoma, and even more importantly, immune checkpoint inhibitors (ICIs)." (PMID 39517999, 2024). "Background and Objectives: The most common mutation in malignant melanoma (MM) is the single-point mutation of v-raf murine sarcoma viral oncogene homolog B1 (BRAF) oncogene." (PMID 38541077, 2024).
melanoma (continued). "In expectation of the high response rate of BRAF/MEKi and sustained efficacy of ICIs, a three‐drug combination of an ICI and BRAF/MEKi is being developed for BRAF‐mutated melanoma." (PMID 38087810, 2024). "BRAF gene mutations occur in a large percentage of cancers, including approximately 50% of melanomas, 20% to 40% of thyroid cancers, and 10% of colorectal cancers." (PMID 38164167, 2024). "Our study demonstrated that the FER1L4 is upregulated in melanocytes and various melanoma cell lines, with expression levels correlated with BRAF mutations, particularly the BRAF V600E variant." (PMID 39764216, 2024). "Despite great progress in the treatment of metastatic melanoma with targeted therapies such as BRAF-inhibitors or immune checkpoint blockade, approximately 55,500 deaths are still caused by melanoma annually." (PMID 38890171, 2024). "The polyclonality framework suggests that primary and metastatic melanoma lesions can harbor BRAF-wild-type and BRAF-mutated subclone populations capable of metastasis." (PMID 39336897, 2024). "On the other hand, BRAF-mutated melanomas typically develop resistance to targeted monotherapy with B-Raf inhibitors within 1 year from commencement, and some of them are primarily resistant to the drugs (vemurafenib, dabrafenib)." (PMID 39018206, 2024). "A correlation has been shown between NRAS mutation and loss of CDKN2A expression through promoter hypermethylation, potentially explaining the loss of p16INK4A in BRAF/MEK inhibitor-resistant melanoma with NRAS mutations." (PMID 39501277, 2024). "Analyses of the literature data have further supported the conclusion that melanomas bearing class II mutations are more sensitive to the combination of BRAF plus MEK inhibitors than to BRAF or MEK inhibitors alone." (PMID 39727691, 2024). "A percentage (38.7%) of patients with multiple primary melanomas were found to have similar dermoscopic features, and these melanomas showed 5.7x higher odds to share the same BRAF mutational status." (PMID 38481925, 2024). "This uncoupling between RICTOR and phospho-AKT levels is consistent with previous evidence of alternative, mTORC2-independent mechanisms of AKT Hydrophobic motif phosphorylation, reported also to occur in BRAF-mutated melanoma cells, including A375." (PMID 38755661, 2024). "BRAF(V600E) is a common gene mutation and is important in the prognosis and treatment options for human colon cancer, thyroid cancer, and melanoma." (PMID 39052013, 2024). "Approximately 30–66% of melanoma cases, including AMs, are carriers of the BRAF gene mutation, which is a target of anti-melanoma therapy." (PMID 39519055, 2024). "We demonstrate that eIF4F is essential for controlling ERK signaling intensity in treatment-naïve melanoma cells harboring BRAF or NRAS mutations." (PMID 39436655, 2024). "So far, three different MEKi namely trametinib, cobimetinib and binimetinib are clinically used against BRAF-mutated melanomas usually in combination with their corresponding BRAF inhibitor." (PMID 38263136, 2024). "Despite both NRAS and BRAF mutations being fairly common in the development of melanoma, rarely do both mutations occur in the same patient." (PMID 38534742, 2024). "The second trial was conducted to study vemurafenib in BRAF V600 mutation-positive non-melanoma cancers." (PMID 38254740, 2024). "They found that Dab/Tram significantly prolonged survival and had fewer skin‐related toxicities, including the development of squamous cell carcinoma in patients with advanced melanoma harboring the BRAF V600E/K mutation." (PMID 38358050, 2024). "Melanomas bearing class II mutations are less sensitive to BRAF inhibitors than those with class I mutations; however, class II-mutant melanomas are sensitive to double inhibition with BRAF and MEK inhibitors." (PMID 39727691, 2024).
melanoma (continued). "RAF inhibitors such as dabrafinib have been shown to be effective in BRAF-mutant melanomas; however, in BRAF-mutant melanomas with concurrent NF1 mutations, RAF inhibitors are less effective due to remaining hyperactive RAS signaling." (PMID 39016685, 2024). "NRAS mutations have been described in about 15-20% of melanoma patients, mutually exclusive with BRAF mutations, except in rare cases." (PMID 39148899, 2024). "The increased use of susceptible detection methods like next-generation sequencing has led to the discovery of various BRAF mutations beyond the V600E/K type in individuals with melanoma." (PMID 39582535, 2024). "Despite modern advancements in systemic therapies, melanoma remains a highly malignant cancer, with persistent resistance to therapies such as checkpoint inhibitors and inhibitors of mutated BRAF V600E." (PMID 39618779, 2024). "The BRAF V600D/R subtype had the highest prevalence in patients with scalp-arising melanoma (3.8% vs. 1.5% on average), reflecting a greater association with hairy skin." (PMID 39735251, 2024). "The BRAF alterations including BRAF V600E mutation is found in many cancers most notably malignant melanomas, anaplastic thyroid cancers and pediatric low grade gliomas." (PMID 39634188, 2024). "This is quite consistent with data presented by our group about the minority of melanoma patients with concurrent high frequency of BRAF mutations and BRAF gene amplification." (PMID 38280995, 2024). "In parallel, belvarafenib, a pan-RAF inhibitor, has been shown to encourage anticancer activity in preclinical melanoma models and patients with BRAF and NRAS mutations." (PMID 39582535, 2024). "One of the most well-known genetic alterations in melanoma is the mutation of the BRAF gene, specifically the p.V600E mutation, which occurs in around 50% of cases." (PMID 38667446, 2024). "NF1-mutated melanomas typically arise on chronically sun-exposed skin or in older individuals, exhibit a high mutation burden, and lack BRAF or NRAS mutations." (PMID 38891988, 2024). "BRAFi is a targeted therapy for melanoma patients with mutations in the BRAF gene, and its use in the clinic has made good progress, but resistance due to long-term dosing remains a clinical challenge." (PMID 39682248, 2024). "First-line treatment, according to the National Comprehensive Cancer Network (NCCN) melanoma guidelines, recommends a combination therapy of BRAFi and MEKi for those with the activating BRAF V600 mutation and metastatic cutaneous melanoma." (PMID 39534873, 2024). "A mutation in the BRAF gene is present in about 40%-60% of melanoma cases, with 80%-90% being a missense V600E mutation, leading to a conformational change in the BRAF protein." (PMID 39534873, 2024). "The different response rates to BRAF V600E‐targeted drugs between BRAF V600E‐mutated melanoma and CRC, and the differential expression pattern of HSPA8 and MYC were consistent with our findings." (PMID 37973552, 2024). "Melanoma cell lines harboring BRAF or NRAS mutations frequently showed low MITF levels and high AXL-RTK levels." (PMID 38672652, 2024). "The PI3K pathway or depletion of the PTEN protein can lead to failure of cellular senescence caused by BRAF mutations, ultimately leading to malignant melanoma." (PMID 39161800, 2024). "Histological characteristics of BRAF-mutated melanomas include superficial spreading and/or nodular growth patterns." (PMID 38247727, 2024). "Significant progress has been made in melanoma therapy in the past two decades with the development of targeted therapeutics against mutated BRAF/MEK and the introduction of immunotherapy." (PMID 38672652, 2024).